METTL2A (methyltransferase 2A, tRNA N3-cytidine)
Description:
S-adenosyl-L-methionine-dependent methyltransferase that mediates N(3)-methylcytidine modification of residue 32 of the tRNA anticodon loop of tRNA(Thr)(UGU) and tRNA(Arg)(CCU). N(3)-methylcytidine methylation by METTL2A requires the N6-threonylcarbamoylation of tRNA (t6A37) by the EKC/KEOPS complex as prerequisite.
Synonyms: METTL2; FLJ12760
Tractability: PROTAC: ubiquitination databases record sites on it.
Gene: Protein-coding gene on chromosome 17 (62,423,875 to 62,453,385, forward strand). Ensembl gene ENSG00000087995.
Subcellular location: Cytoplasm
Gene Ontology:
Molecular function: protein binding; tRNA (cytidine-3-)-methyltransferase activity; RNA methyltransferase activity; S-adenosylmethionine-dependent methyltransferase activity
Biological process: tRNA metabolic process; tRNA methylation; tRNA modification
Cellular component: cytoplasm
Genetic constraint (gnomAD): Loss-of-function variants: 42 observed, 43.82 expected, observed/expected ratio (o/e) 0.96, 90% interval 0.75 to 1.24. The synonymous counts are far from expectation, so gnomAD's model fits this gene poorly and the ratio says little. Missense variants: 333 observed, 409.66 expected, observed/expected ratio (o/e) 0.81, 90% interval 0.74 to 0.89. Synonymous variants: 109 observed, 148.9 expected, observed/expected ratio (o/e) 0.73, 90% interval 0.63 to 0.86.
Homologues: Orthologues: chimpanzee METTL2A (98% identical), dog METTL2A (89% identical), rat Mettl2 (80% identical), mouse Mettl2 (79% identical), zebrafish mettl2a (63% identical), tropical clawed frog mettl2b (60% identical). Paralogues in human: METTL2B (98% identical), METTL8 (51% identical), METTL6 (32% identical).
Diseases named in the same sentence as METTL2A in open-access papers:
METTL2A is named in the same sentence as 18 diseases in open-access papers, as found by Europe PMC text mining. Sharing a sentence is not in itself a finding about the gene and the disease. The quoted sentences say what the papers report.
breast carcinoma (5 papers, 2012 to 2024). "Recent studies have shown that METTL2A is a potential oncogene in breast cancer, and high expression of METTL2A leads to elevated levels of m3C modification associated with cell proliferation and activation of the pathway." (PMID 39019857, 2024). "From the GSE3744 data analysis, we observed METTL2A was significantly overexpressed in breast cancer tissues." (PMID 36266694, 2022). "METTL2A had high-level amplifications in two TCGA tumor types: breast cancer (BRCA, 6.73%) and mesothelioma (MESO, 5.75%)." (PMID 34285249, 2021). "Overexpression of METTL2A/B was linked with prostate cancer metastasis, cAMP response element-binding (CREB) regulation in myeloid leukemia, and breast cancer patients' response to chemotherapy." (PMID 22291905, 2012). "However, in other tumors, METTL2a is a potential N3 methylcytidine (M3C)—the related gene that promotes breast cancer development." (PMID 38130905, 2023). "The consistency of our results indicates that breast cancer cells with high METTL2A expression could be active in proliferation and DNA damage response pathways." (PMID 36266694, 2022). "Furthermore, we determined the correlation of METTL2A expression with clinical parameters of patients with breast cancer and analyzed related signaling pathways and potential therapeutic agents of METTL2A in BRCA patients." (PMID 36266694, 2022). "Importantly, METTL2A has been intensely explored as a potential oncogene in BRCA, to aid the development of potential drug agents for precision therapy in breast cancer patients." (PMID 36266694, 2022). "The expression of METTL2A was higher in HER2 positive and ER positive breast cancer patients." (PMID 36266694, 2022).
breast tumor (2 papers, 2022 to 2024). "METTL6 acts as an oncogene in luminal breast tumors and hepatocarcinoma, and METTL2A also seems to play a role in breast cancer." (PMID 38918637, 2024). "Meanwhile, the genes with r > 0.3 and P < 0.05 in TCGA were included for GO enrichment analysis to study METTL2A related GO pathway in breast tumor tissue." (PMID 36266694, 2022).
mesothelioma (2 papers, 2021 to 2022). A usually malignant and aggressive neoplasm of the mesothelium which is often associated with exposure to asbestos. "The top three cancer types with genetic alteration of METTL2A is BRCA(7%), Mesothelioma (6%), and Lymphoid Neoplasm Diffuse Large B-cell Lymphoma (4%)." (PMID 36266694, 2022).
glioma (1 paper, 2024). A benign or malignant brain and spinal cord tumor that arises from glial cells (astrocytes, oligodendrocytes, ependymal cells). "In glioma cells, it was observed that the expression of genes related to MRM, like GTPBP3, METTL2A, METTL6, METTL8, NSUN4, and TRMT61A, showed positive correlation with the expression of HAVCR2, PVR, TNFRSF25 and TNFSF15 as revealed by scRNA-seq analysis." (PMID 38824202, 2024). "The expression of HAVCR2, PVR, TNFRSF25, and TNFSF15 showed a positive correlation with the expression of numerous MRM-related genes like GTPBP3, METTL2A, METTL6, METTL8, NSUN4, and TRMT61A in glioma cells." (PMID 38824202, 2024).
Pan (1 paper, 2021). "We found that, similar to the TCGA Pan-Cancer cohort, at least ten METTLs (e.g. METTL1, METTL2A, METTL2B, EEF1AKNMT) showed high-level amplifications in more than 2% of CCLE lines." (PMID 34285249, 2021).
Thyroid carcinoma (1 paper, 2022). "In contrast, there was down-regulation of these four genes in Kidney Chromophobe (KICH), Kidney renal clear cell carcinoma (KIRC), and Thyroid carcinoma Compared to METTL8, the other three genes (METTL2A, METTL2B and METTL6) exhibited a more homogenized co-expression in various cancer types." (PMID 36266694, 2022).
tumor (4 papers, 2021 to 2025). "The results revealed that eight tumor hallmarks were enriched in the METTL2A high-expression subgroup, which included UNFOLDED_PROTEIN_RESPONSE, MYC_TARGETS_V1, G2M_CHECKPOINT, E2F_TARGETS, DNA_REPAIR, MYC_TARGETS_V2, MTORC1_SIGNALING AND MITOTIC_SPINDLE." (PMID 36266694, 2022). "Consistently, the protein level of METTL2A was significantly higher in BRCA tumor tissues compared with normal tissues in CPTAC database." (PMID 36266694, 2022). "Using IHC and CPTAC, we found that the protein level of METTL2A was up-regulated in BRCA tumor tissues." (PMID 36266694, 2022). "Taken together, several METTL genes, including METTL1, METTL2A, METTL4, EEF1AKNMT, and METTL24, had relatively higher frequencies of genetic amplification, deletion, or mutation in various tumor types, notably LUAD, BRCA, and GBM." (PMID 34285249, 2021). "Interestingly, compared with METTL8 and METTL6, differential expression of METTL2A in BRCA tumor tissues and adjacent normal tissues was more significantly." (PMID 36266694, 2022). "Finally, we detected METTL2A expression in tumor tissues of BRCA using immunohistochemistry." (PMID 36266694, 2022). "The expression levels of ATXN3, METTL2A, PEX26 and UGGT1 in tumour cells were higher than those in normal mammary epithelial cells, and their expression in BRCA tissues was higher than that in normal adjacent tissues." (PMID 40995818, 2025). "The expression levels of ATXN3 | chr14:92526779, LOC100130744 | chr5:14716392, METTL2A | chr17:60528133, PEX26 | chr22:18572607 and UGGT1 | chr2:128949284 in tumour tissues were significantly higher than those in normal tissues (p < 0.05)." (PMID 40995818, 2025). "The differential expression analysis of METTL2A, METTL2B METTL6 and METTL8 was conducted between tumor tissue and normal tissue in 24 different cancer types." (PMID 36266694, 2022). "We again found that a small number of METTLs, including METTL1 and METTL2A, were significantly elevated, while METTL7A was significantly decreased at the protein level in tumor tissue compared to NATs." (PMID 34285249, 2021). "Interestingly, expression of METTL2A, METTL2B, and METTL6 mRNA is elevated in most tumor types compared with corresponding normal tissues and is associated with poor prognosis." (PMID 38982125, 2024). "The IHC result showed that METTL2A protein expression was higher in tumor tissues compared to adjacent noncancerous tissues." (PMID 36266694, 2022).
cancer (3 papers, 2021 to 2024). A tumor composed of atypical neoplastic, often pleomorphic cells that invade other tissues. "The m3C associated genes showed aberrant expression in 17 cancer types for METTL2A, 15 cancer types for METTL2B, 14 cancer types for METTL6 and 13 cancer types for METTL8." (PMID 36266694, 2022). "The data and analyses suggest that m3C associated genes, especially METTL2A, play a key function and are tightly linked to the development of various cancers." (PMID 36266694, 2022). "Of the 30 METTLs, expressions of eight (METTL1, METTL7B, METTL5, NTMT1, METTL2A, METTL2B, EEF1AKNMT, METTL6) were significantly (FDR < 0.05) associated with unfavorable overall survival across cancers." (PMID 34285249, 2021). "The N3-methylcytidine (m3C) gene, METTL2A, is highly expressed in breast invasive carcinoma (BRCA), and differential analysis showed that METTL2A was differentially expressed in cancer and paracancerous tissues more strongly than METTL6 and METTL8." (PMID 39289775, 2024). "We identified a subset of METTL genes, notably METTL1, METTL2A, METTL2B, METTL7B, NTMT1, and METTL26, with high frequencies of genomic amplification and/or up-regulation, while METTL7A and METTL24 were under-expressed, at both mRNA and/or protein levels in a spectrum of human cancers." (PMID 34285249, 2021). "In this study, we found that several METTLs, such as METTL2A, METTL2B, and METTL26, which have not been previously investigated systematically, are upregulated at mRNA and protein levels in a subset of human cancers compared to normal tissue." (PMID 34285249, 2021).
METTL2A also shares sentences with these, for which no sentence is quoted: Adrenocortical carcinoma (1 paper); breast invasive carcinoma (1); diffuse large B-cell lymphoma (1); Esophageal carcinoma (1); lymphoid neoplasm (1); myeloid leukemia (1); pancreatic adenocarcinoma (1); prostate carcinoma (1); rectum adenocarcinoma (1); uveal melanoma (1).